LAPTM4B (lysosomal protein transmembrane 4 beta)
Diseases named in the same sentence as LAPTM4B in open-access papers (continued):
Sharing a sentence is not in itself a finding about the gene and the disease.
lung carcinoma (9 papers, 2007 to 2025). "Beyond HCC, LAPTM4B has been implicated in tumor cell invasion and metastasis across multiple malignancies, including lung cancer, clear cell renal carcinoma, and osteosarcoma." (PMID 40661135, 2025). "It is plausible to surmise that analysis of a relatively larger series of NSCLC specimens (n = 368) in our study allowed us to shed light on more specific associations of LAPTM4B expression with lung cancer prognosis." (PMID 26343532, 2015). "Our findings insinuate that LAPTM4B is an important mediator of autophagy for survival of lung cancer cells during serum starvation." (PMID 26343532, 2015). "We also demonstrated that LAPTM4B promoted survival and autophagy as well as activated the NRF2 stress response pathway in lung cancer cells, particularly those with mutations in the KRAS oncogene, under serum deprived conditions." (PMID 26343532, 2015). "Our study provides new insights into the oncogenic signaling function of LAPTM4B in lung cancer cells and its cross talk with other canonical pathways such as NRF2/HMOX1." (PMID 26343532, 2015). "Our study points to the relevance of LAPTM4B expression to NSCLC pathogenesis as well as to the probable role of LAPTM4B/NRF2 signaling in promoting lung cancer cell survival." (PMID 26343532, 2015). "Our microarray transcriptome profiling and pathways analyses provide additional insights into the impact of LAPTM4B expression on oncogenic cellular signaling in lung cancer cells." (PMID 26343532, 2015). "We were prompted to examine the impact of LAPTM4B expression on growth inhibitory effects of serum starvation in lung cancer cells." (PMID 26343532, 2015). "Knockdown of LAPTM4B expression inhibited cell growth, induced cellular apoptosis and decreased cellular autophagy in serum starved lung cancer cells." (PMID 26343532, 2015). "We also found that LAPTM4B expression was important for survival and promotion of autophagy in lung cancer cells under serum starvation." (PMID 26343532, 2015). "Similarly, in lung cancer cells, miR-27b-3p can directly target LAPTM4B mRNA and inhibit the protein expression of LAPTM4B to inhibit the growth and metastasis of lung cancer cells." (PMID 40231269, 2025). "In addition, a topologically organized gene network mediated by NRF2 was found to be enriched with genes that were preferentially down-regulated by LAPTM4B knockdown in serum starved lung cancer cells including various anti-oxidant genes (e.g. HMOX1)." (PMID 26343532, 2015). "Notably, the analysis revealed that the NRF2 transcription factor exhibited the lowest Z score and activated state following LAPTM4B knockdown in serum starved lung cancer cells." (PMID 26343532, 2015). "Deng found that LAPTM4B*2 was a risk factor for lung cancer, while Li reported that LAPTM4B*2 was not closely associated with a susceptibility to lung cancer." (PMID 24746178, 2014). "Our gene expression profiling coupled with functional pathways analysis revealed that LAPTM4B expression promoted the NRF2 stress response and pathway in lung cancer cells deprived of serum." (PMID 26343532, 2015). "Our study points to new mechanisms of NRF2 activation as well as to targets, e.g. LAPTM4B/NRF2 signaling axis, for development of new strategies for lung cancer therapy." (PMID 26343532, 2015). "In the present study, we sought to characterize LAPTM4B expression in NSCLC specimens and its impact on lung cancer cell malignant phenotype and cell signaling in vitro." (PMID 26343532, 2015). "We also demonstrated that in serum deprived lung cancer cells, LAPTM4B protein indeed co-localized with LC3 suggestive of the implication of LAPTM4B in autophagic flux and autolysosome formation." (PMID 26343532, 2015). "Moreover, our gene expression profiling coupled with functional pathways analyses revealed that LAPTM4B promoted the NRF2 stress response and pathway in lung cancer cells grown under serum deprived conditions." (PMID 26343532, 2015).
lung carcinoma (continued). "Notably, our recent study demonstrated that lysosomal protein transmembrane 4 beta (LAPTM4B) is largely elevated in airways closest to tumors and in NSCLCs compared to normal lung tissues as well as promotes anchorage-independent growth of lung cancer cells." (PMID 26343532, 2015).
lymph node metastasis (9 papers, 2012 to 2019). "Overexpression of LAPTM4B-35 was significantly associated with degree of differentiation, depth of invasion, lymphovascular invasion and lymph node metastasis (P<0.05)." (PMID 25849595, 2015). "The overexpression of LAPTM4B-35 was significantly associated with the lymph node metastasis, seminal vesicle invasion, PCa stage, higher Gleason score, higher preoperative PSA, and biochemical recurrence (BCR)." (PMID 24651764, 2014). "LAPTM4B*2 was significantly associated with higher histopathologic grade, lymph node metastasis and poor prognosis." (PMID 22984585, 2012). "Furthermore, serum LAPTM4B levels were positively correlated with smoking, advanced clinical stages, lymph node metastasis, ALK rearrangements and EGFR mutations." (PMID 30940109, 2019). "In addition, the expression levels of LAPTM4B were positively correlated with advanced clinical stages, lymph node metastasis and EGFR mutations." (PMID 30940109, 2019). "Furthermore, LAPTM4B-35 expression was associated with lymphovascular invasion (P = 0.000), depth of invasion (P = 0.016) and lymph node metastasis (P = 0.029)." (PMID 25849595, 2015). "A total of 14 patients (19.4%) had high LAPTM4B-35 expression in both the primary tumour and lymph node metastasis." (PMID 31827181, 2019). "LAPTM4B *1/1 was more frequently detected in colon cancer patients with lymph node metastasis and TNM III+IV stages in total colon cancer (discovery + testing cohorts)." (PMID 27391361, 2016). "High LAPTM4B-35 expression was significantly correlated with higher PCa stage, seminal vesicle invasion, lymph node metastasis, higher preoperative PSA, higher Gleason score, and BCR, but not with age, surgical margin status, and angiolymphatic invasion." (PMID 24651764, 2014). "LAPTM4B genotype (RR, 2.740, 95%CI, 1.549-4.846, P = 0.001) and lymph node metastasis (RR, 2.604, 95%CI, 1.368-4.955, P = 0.004) are also prognostic markers for disease-free survival in these patients (P<0.05)." (PMID 22984631, 2012). "In 29.2% of the corresponding lymph node metastases, LAPTM4B-35 was expressed at a high intensity." (PMID 31827181, 2019). "High expression of LAPTM4B-35 in lymph node metastasis was found in 29.2% of cases." (PMID 31827181, 2019). "Furthermore, LAPTM4B *1/1 tended to be frequently detected in patients with lymph node metastasis and TNM III+IV stages in total colon cancer cases." (PMID 27391361, 2016). "Then, we investigate LAPTM4B protein levels in 63 LAC tissues by IHC and our results revealed that high expression of LAPTM4B correlated with aggressive clinicopathological features (including advanced clinical stages, lymph node metastasis and EGFR mutations)." (PMID 30940109, 2019). "LAPTM4B-35 expression was significantly higher in the higher PCa stage and seminal vesicle invasion cases; LAPTM4B-35 expression was also significantly increased in PCa patients with lymph node metastasis, higher preoperative PSA, higher Gleason score, and BCR." (PMID 24651764, 2014). "However, the clear association of LAPTM4B *2 with poor histopathologic differentiation, higher TNM stage and presence of lymph node metastasis argues that it is a significant factor in the highly malignant phenotype of gallbladder carcinoma and therefore warrants further investigation." (PMID 22984631, 2012). "Serum LAPTM4B levels of LAC patients were significantly correlated with smoking, advanced clinical stages, lymph node metastasis, anaplastic lymphoma kinase (ALK) rearrangements and EGFR mutations." (PMID 30940109, 2019). "We found that genotype *2 of the LAPTM4B gene was significantly associated with poor histopathologic differentiation, higher TNM stage and lymph node metastasis (P<0.05), but not with age, gender, or tumor size (P>0.05)." (PMID 22984631, 2012).
non-small cell lung carcinoma (8 papers, 2015 to 2026). A group of at least three distinct histological types of lung cancer, including non-small cell squamous cell carcinoma, adenocarcinoma, and large cell carcinoma. "Knocking down LAPTM4B in Hela cells and non-small cell lung cancer attenuated cell growth, according to cell counting kit 8 (CCK8) assays." (PMID 40231269, 2025). "In colorectal carcinoma, patients with high LAPTM4B-35 expression had a worse OS and DFS17.In non-small-cell lung cancer, LAPTM4B-35 overexpression was associated with significantly worse 5-year OS and progression free survival." (PMID 31827181, 2019). "We recently demonstrated that lysosomal protein transmembrane 4 beta (LAPTM4B) is elevated in non-small cell lung cancers (NSCLCs) and in the surrounding premalignant airway field of cancerization." (PMID 26343532, 2015).
gallbladder carcinoma (7 papers, 2012 to 2025). "In gallbladder cancer cells, overexpression of LAPTM4B showed a tendency to inhibit apoptosis, especially under Epirubicin treatment." (PMID 40231269, 2025). "In this regard, the amplification of laptm4a and laptm4b genes has been reported in numerous chemoresistant tumors, including breast and gallbladder cancer." (PMID 29292724, 2017). "In this study, we tested for LAPTM4B genotype by PCR assay in 85 patients who had surgical resection for gallbladder carcinoma." (PMID 22984631, 2012). "This is the first time correlation of LAPTM4B genotype with prognosis and clinicopathologic features has been demonstrated in gallbladder carcinoma." (PMID 22984631, 2012). "In this study we investigated the correlation of LAPTM4B genotype with prognosis and clinicopathologic features in patients who had undergone curative resection for gallbladder carcinoma (GBC)." (PMID 22984631, 2012). "In gallbladder cancer, an MTT assay and flow cytometry experiments also confirmed that overexpression of LAPTM4B promoted the proliferation of gallbladder cancer cells." (PMID 40231269, 2025).
ovarian carcinoma (7 papers, 2012 to 2025). A malignant neoplasm originating from the surface ovarian epithelium. "Association analysis between HIF-1α, MDR1 and LAPTM4B expression in ovarian cancer blood specimens." (PMID 30746305, 2019). "This ceramide-interacting protein, across quaternary membranes, can modulate the mTOR signaling pathway associated with autophagy; LAPTM4B expression has been shown to be a poor prognostic marker in ovarian cancer." (PMID 36937841, 2023). "Correlation of HIF-1α, MDR1, and LAPTM4B expression with clinico-pathological features of ovarian cancer." (PMID 30746305, 2019). "In ovarian cancer, we observed an association of elevated HIF-1α, MDR1 and LAPTM4B expression with advance tumor stage, metastasis and pre-treated." (PMID 30746305, 2019). "Yin and colleagues found an association of LAPTM4B expression with stage III and chemotherapy resistance in patients who are taking PAC (cisplatin, epirubicin and cyclophosphamide) regimen in ovarian cancer." (PMID 30746305, 2019). "In case of ovarian cancer 27 patients were those having high expression of HIF-1α, MDR1 and LAPTM4B while 10 patients were those having low expression of all the three genes, which showed a positive linear correlation among these genes (R = 0.849, p < 0.001)." (PMID 30746305, 2019).
cervical carcinoma (6 papers, 2012 to 2025). A carcinoma arising from either the exocervical squamous epithelium or the endocervical glandular epithelium. "A study with the cervical cancer cell line HeLa demonstrated that RNAi-mediated knockdown of LAPTM4B-35 inhibited proliferation, invasion and angiogenesis in vitro." (PMID 31827181, 2019). "In cervical carcinomas, which in most cases are associated with HPV infection, high expression of LAPTM4B-35 was also related to poor OS and DFS16." (PMID 31827181, 2019). "Previous studies have demonstrated that LAPTM4B mRNA and protein are significantly up-regulated in a wide variety of cancers such as lung cancer, gallbladder carcinoma, extra-hepatic cholangiocarcinoma, cervical carcinoma, colon cancer and ovarian cancer." (PMID 22509374, 2012). "Subsequently, they verified that the coexpression of LAPTM4B and VEGF resulted in poor prognosis for cervical cancer." (PMID 28476037, 2017). "Recent studies have also shown that silencing LAPTM4B remarkably reduces the expression of VEGF in HeLa cells and that increased LAPTM4B-35 combined with positive VEGF expression might serve as a new biological marker to predict outcomes in cervical carcinoma." (PMID 28476037, 2017).
colon carcinoma (6 papers, 2007 to 2019). "In the current study there was an association of HIF-1α, MDR1 and LAPTM4B expression with advanced tumor stage, metastasis and chemotherapy treated group in breast, ovarian, prostate and colon cancer patients." (PMID 30746305, 2019). "In colon cancer cases, the LAPTM4B *2 allele frequency was 34.2%, which is different from that in rectal and esophageal cancer cases (27.8% and 23.8%, respectively)." (PMID 27391361, 2016). "Association analysis between HIF-1α, MDR1 and LAPTM4B expression in colon cancer blood specimens." (PMID 30746305, 2019). "Our findings on LAPTM4B alleles in colon cancer provide additional evidence that different LAPTM4B isoforms might play various roles, that is, LAPTM4B-35 can activate PI3K/Akt pathway and LAPTM4B -24 can activate mTORC1 pathway." (PMID 27391361, 2016). "Moreover, patients with LAPTM4B *1 allele had a poorer prognosis than LAPTM4B *2 allele in total colon cancer cases (OS rate 33.8% vs. 50.5%, P = 0.0050)." (PMID 27391361, 2016). "Correlation of HIF-1α, MDR1, and LAPTM4B expression with clinico-pathological features of colon cancer." (PMID 30746305, 2019). "There was 12–13 fold increased in expression of HIF-1α, two fold increased in MDR1 and 13–14 fold increased in LAPTM4B mRNA level in peripheral blood of breast, ovarian, prostate and colon cancer patients." (PMID 30746305, 2019). "For the clinicopathological parameters, LAPTM4B genotype was correlated with recurrence in total colon cancer, especially for LAPTM4B *2/2 which decreased in recurrent colon cancer patients." (PMID 27391361, 2016). "Among 167 colon cancer cases, the LAPTM4B genotypes: *1/1, *1/2 and *2/2 frequencies were 44.6%, 42.3% and 13.1%, respectively." (PMID 27391361, 2016). "The same tendency of LAPTM4B *1/1 and LAPTM4B *1 was observed in the colon discovery and testing cohorts of colon cancer (P = 0.0417 and 0.0444, P = 0.0254 and 0.0292, respectively)." (PMID 27391361, 2016). "Genotypes of LAPTM4B were determined by PCR in 167 colon cancer cases (72 patients in a discovery cohort and 95 patients in a testing cohort), 160 rectal cancer cases and 164 esophageal cancer cases." (PMID 27391361, 2016). "Hence, this study was aimed to measure the co-expression of HIF-1α, MDR1 and LAPTM4B genes in blood of breast, ovarian, prostate and colon cancer patients and matched with appropriate controls." (PMID 30746305, 2019). "As a result, the different LAPTM4B isoforms may play diverse functions in LAPTM4B *1 patients when compared with LAPTM4B *2 patients with colon cancer." (PMID 27391361, 2016). "However, LAPTM4B*1 was more frequently detected in colon cancer patients with moderate and well differentiation in colon discovery cohort." (PMID 27391361, 2016). "Whereas in our study, LAPTM4B *1 allele shows a significant correlation with overall survival of colon cancer patients, but not in rectal and esophageal cancer patients." (PMID 27391361, 2016). "However, LAPTM4B genotype will be a useful biomarker for colon cancer patients when considering curative surgical resection." (PMID 27391361, 2016). "LAPTM4B *2/2 decreased in recurrent patients in total colon cancer patients (P = 0.045)." (PMID 27391361, 2016). "In the present study, we revealed an independent prognostic role of LAPTM4B gene polymorphism in colon cancer patients who received surgical resection, but not in rectal and esophageal cancers." (PMID 27391361, 2016). "However, LAPTM4B*1 was more frequently detected in colon cancer patients with moderate and well differentiation in colon discovery cohort (P = 0.011)." (PMID 27391361, 2016). "Kaplan-Meier survival analysis and log-rank test indicated that colon cancer patients with LAPTM4B *1/1 genotype showed a shorter overall survival (OS) when compared with those with LAPTM4B *1/2 and LAPTM4B *2/2 genotypes (OS rate 33.8% vs. 43.7% and 72.7%, P = 0.0025)." (PMID 27391361, 2016).
colon carcinoma (continued). "LAPTM4B genotype status might be a useful prognostic indicator for patients that need surgical operation in colon cancer." (PMID 27391361, 2016). "Furthermore, the Cheng study indicated that the LAPTM4B polymorphism was associated with the development of colon cancer, but not with rectal or oesophageal cancers." (PMID 24746178, 2014). "In colon cancer, high expression of HIF-1α, MDR1 and LAPTM4B was correlated to clinical features of patients." (PMID 30746305, 2019). "In colonic cancer patients, a similar trend was observed where high HIF-1α, MDR1 and LAPTM4B expression was correlated with advanced tumor stage, metastasis as well as chemotherapy treatment in isolated studies." (PMID 30746305, 2019). "In case of colon cancer 12 patients were those having high expression of HIF-1α and MDR1 while 15 were those with high expression of LAPTM4B also harboring high expression of MDR1 and HIF-1α." (PMID 30746305, 2019). "LAPTM4B *2/2 decreased in recurrent patients compared with non-recurrent ones in total colon cancer patients (P = 0.045, 7.4% vs. 20.5%) and in discovery and testing cohort (P = 0.203, 7.1% vs. 22.7% and P = 0.368, 7.6% vs. 17.2%, respectively)." (PMID 27391361, 2016). "Patients with LAPTM4B *1 (genotypes *1/1) had a significantly poorer overall survival when compared with LAPTM4B *2 (genotypes *1/2 or *2/2) patients in colon cancer (discovery and testing cohorts), but not in rectal and esophageal cancers." (PMID 27391361, 2016). "Kaplan-Meier survival curves and Log-rank test showed that LAPTM4B*1 was correlated with shorter overall survival (OS) in discovery and testing cohorts of colon cancer (P = 0.0254 and 0.0292, respectively), but not in rectal and esophageal cancer cases (P = 0.7669 and 0.9356, respectively)." (PMID 27391361, 2016).